INS (insulin)
Diseases named in the same sentence as INS in open-access papers (continued):
Sharing a sentence is not in itself a finding about the gene and the disease.
Insulin resistance (continued). "A limitation stems from the use of FSI as a surrogate measure of insulin resistance in our data, but previous studies have shown that fasting insulin is a valid and reliable surrogate measure of insulin resistance." (PMID 18307789, 2008). "Insulin resistance is marked by hyperinsulinemia,enhanced hepatic gluconeogenesis, and impaired insulin-stimulated glucoseuptake into skeletal muscle and fat." (PMID 18288286, 2008). "To create a more specific parameter of insulin resistance that combines serum glucose with serum insulin levels, we decided to calculate an insulin glycaemic index (insulin × glucose/22.5) at each time point." (PMID 19087258, 2008). "It is possible that the intergenerational transmission of developmentally programmed insulin resistance is determined in part by the relative insulin sensitivity of the mother during pregnancy/lactation." (PMID 18928547, 2008). "The significantly elevated insulin resistance often encountered in broad critical care cohorts challenges the practice of using insulin-only protocols." (PMID 18412978, 2008). "Statistics have shown that over 30% of Canadian adults have insulin resistance and that about 50% of salt-sensitive subjects are insulin resistant." (PMID 18570670, 2008). "Cortisol has been shown to induce insulin resistance by increasing hepatic glucose production, suppressing glucose usage, and inhibiting insulin secretion." (PMID 18254945, 2008). "Severalsoluble mediators are involved in the development of insulin resistance,through generating insulin signaling dysfunction." (PMID 18604303, 2008). "These animals exhibit impaired oxidative phosphorylation in skeletal muscle, mild peripheral insulin resistance and β-cell secretory defects very early in life but have adequate compensatory insulin secretion for several weeks." (PMID 18485240, 2008). "The triggering complications include metabolic acidosis, decreased insulin action (including insulin resistance), increased glucocorticoid production, high levels of Ang II, and inflammation." (PMID 17987322, 2008). "The observed trend in the hypersecretion of endogenous insulin was paralleled by an increase in the HOMA calculation of insulin resistance which increased significantly, two-fold and three-fold in the progression from NG to IGT and DM, respectively." (PMID 18516349, 2008). "Although both increased insulin secretion andreduced insulin resistance can improve IPGTT, lowered insulin level andimproved IPGTT in our study are beneficial to the reduction of insulinresistance." (PMID 19096709, 2008). "Insulin resistance has traditionally been defined from a glucocentric view—i.e., when a defect in insulin action results in fasting hyperinsulinaemia to maintain euglycaemia." (PMID 18949082, 2008). "Studies indicate that insulin resistance can be induced by stimulating the degradation of important molecules in the insulin signaling pathway, in particular the insulin receptor substrate proteins IRS1, IRS2 and the kinase AKT1 (Akt)." (PMID 19007436, 2008). "• To investigate the effectiveness of vitamin D supplementation in improving insulin sensitivity in women with hypovitaminosis D who have demonstrated insulin resistance, and/or lipid profiles in those with dyslipidaemia." (PMID 18667086, 2008). "In obesity-prone populations, insulin resistance more accurately predicts development of T2D than does insulin secretory dysfunction." (PMID 18498634, 2008). "Type 2 diabetes (T2D) is a common disease characterized by insulin resistance and reduced insulin secretion." (PMID 18598350, 2008). "During the pathogenesis of type 2 diabetes, peripheral tissues, such as liver, skeletal muscle, and adipose tissue, develop insulin resistance which provokes compensatory increments in pancreatic insulin secretion." (PMID 18714373, 2008).
Insulin resistance (continued). "Inhumans, the blockade of IL-1 with IL-1 RA improves glycaemia and beta-cellsecretory function and reduces markers of systemic inflammation.Accordingly, IL-1 has been shown to induce insulin resistance mainly byinhibiting insulin-mediated signaling." (PMID 18604303, 2008). "This novel disease model exhibits fasting hyperglycaemia and hyperinsulinaemia, enhanced insulin secretion, tissue specific insulin resistance hypertriglyceridemia and structural changes in the endocrine pancreas and the kidney." (PMID 18698428, 2008). "The decreased sensitivity to insulin in Dahl S rats may arise from a common variant (s) in genes along the insulin signaling and/or inflammatory pathways that triggers a powerful inflammatory response and enhance overt insulin resistance in Dahl S rats in excessive salt environment." (PMID 18570670, 2008). "Insulin resistance also leads to the impairment of other biological actions of insulin, including its effects on lipid and protein metabolism, vascular endothelial function and gene expression." (PMID 18553029, 2008). "In obese rodents, increased IKKactivity or overexpressed IKK promotes insulin resistance, whereas reduction ofIKK activity or IKKβ expressionimproves insulin sensitivity." (PMID 18566691, 2008). "Among these, FFAs have to beconsidered as proatherosclerotic agents, capable of interfering with insulin signalingand provoking insulin resistance." (PMID 18604303, 2008). "Insulin resistance is a pathological state where peripheral tissues, particularly skeletal muscle, fail to respond to circulating insulin." (PMID 19787081, 2008). "They suffer from a chronic state of insulin resistance, with inhibition of the insulin-signaling cascade by free fatty acids or by inflammatory cytokines, such as TNFα." (PMID 19055829, 2008). "As shown in a previous study, about 16% people with normal weight (BMI < 25 kg/m2) was identified to be insulin resistant; thus search for clinically simple and useful biomarkers to detect insulin resistance among people with normal weight is necessary." (PMID 18307789, 2008). "Fasting is reported to enhance insulin-induced IRS-1 and IRS-2 tyrosine phosphorylation and association with PI3-kinase in liver and muscle of animal models of insulin resistance (streptozotocin treated rats)." (PMID 18570670, 2008). "We used an insulin glycaemic index to quantify insulin resistance, which is less precise than an insulinic clamp, the gold standard for the assessment of insulin resistance." (PMID 19087258, 2008). "The combined insulin resistance classes (defined as IGT or increasing levels of insulin at 120 min after the glucose challenge) amount to a total of 895 females, or 33.4% of the female study population." (PMID 18611252, 2008). "Insulin usually suppresses hepatic glucose production, and a key feature of the insulin resistance in type 2 diabetes is increased glucose output from the liver via gluconeogenesis." (PMID 19007436, 2008). "First, LA has been shown to mitigate insulin resistance in GK rats, and it has also been shown that improvement of insulin sensitivity is mediated by activation of AMPK and reduced triglyceride accumulation in skeletal muscle." (PMID 18523557, 2008). "Insulin resistance is a disorder in which target cells fail to respond to ordinary levels of circulating insulin, hence higher than normal concentrations of insulin are needed in order to maintain normoglycemia." (PMID 18500989, 2008). "This cell line was previously used to determine the role of PI3K/Akt pathway in insulin signaling and, by incubating in high-glucose medium, was used as in vitro model of insulin resistance." (PMID 19114996, 2008). "In dietary trials, replacement of saturated fatty acids with polyunsaturated fatty acids has improved insulin sensitivity and decreased abdominal obesity, whereas substituting saturated fatty acids for unsaturated fatty acids results in insulin resistance." (PMID 18612464, 2008).
Insulin resistance (continued). "Insulin resistance consists of impairment of the ability of insulin to control hepatic glucose production and enhance glucose clearance in target tissues." (PMID 18553029, 2008). "HOMAir is an index of insulin resistance that is derived from fasting glucose and insulin, and correlates inversely in rodents with insulin sensitivity measured by euglycemic clamp." (PMID 18682834, 2008). "The finding that in all groups of mice plasma insulin levels failed toreturn to basal within 2 hours after the glucose load is in accordance withhigh-fat diet inducing insulin resistance." (PMID 18497871, 2008). "Persistent insulin resistance and dyslipidemia, together with the elevation of plasma insulin levels and lipoprotein a with GH replacement, are of concern in these patients." (PMID 20108502, 2008). "For instance, in both animal and human studies, vitamin D depletion was significantly related to insulin resistance and impaired insulin secretion." (PMID 19015731, 2008). "Defects in skeletal muscle insulin signaling have been extensively studied, and much is now known about obesity and Type 2 diabetes which can help explain insulin resistance in these populations." (PMID 18652694, 2008). "Inhibition of FAK prevents insulin-stimulated remodeling of actin filaments resulting into decreased Glut-4 translocation and glucose uptake generating insulin resistance." (PMID 18771597, 2008). "MUFA-rich diet prevents insulin resistance induced by a carbohydrate-rich diet in insulin-resistant subjects." (PMID 18950537, 2008). "We have recently extended these findings to humans, demonstrating insulin resistance in muscle with insulin sensitization in subcutaneous adipose tissue." (PMID 18340018, 2008). "Insulin resistance, which characterizes type 2 diabetes, is manifested by decreased insulin-stimulated glucose transport and metabolism." (PMID 19114996, 2008). "Regulation of glucose uptake in muscle cells via Glut-4 is a fundamental action of insulin and gets disrupted in insulin resistance." (PMID 18771597, 2008). "Conversely, over-expression of p85α is correlated with skeletal muscle insulin resistance in obesity and type 2 diabetes and has been reported in insulin-resistant states induced by e.g. growth hormone excess and short-term overfeeding." (PMID 19011679, 2008). "The insulin resistance is defined as an impaired ability of plasma insulin to promote peripheral glucose disposal, suppress hepatic glucose, and inhibit very low density lipoprotein (VLDL) output." (PMID 18700035, 2008). "Carbohydrate restriction improves insulin resistance by lowering insulin levels and the disinhibition of hormone sensitive lipase, promoting triacylglycerol hydrolysis." (PMID 18289377, 2008). "This work will add to current research by directly comparing these markers of insulin resistance (fasting insulin) and insulin secretion (fasting glucose and HbA1c) within the same study population and by exploring these associations in older women." (PMID 17760500, 2007). "This indicates that with the increased severity of the burn injury insulin resistance increases and more insulin needs to be synthesized to maintain normoglycemia." (PMID 17716366, 2007). "In our earlier work, we reported that common lipid transfection reagents are able to induce a state of cellular insulin resistance which hampers significantly subsequent experiments designed to examine insulin signal transduction." (PMID 17309805, 2007). "The agreement between World Health Organization and European Group for Study of Insulin Resistance definitions, the definitions that require the measurement of insulin sensitivity and fasting insulin levels is very good." (PMID 18088443, 2007). "Placenta is an insulin independent organ and therefore gestational insulin resistance is expected to divert more nutrients through the placenta." (PMID 17437648, 2007).
Insulin resistance (continued). "High insulin resistance or a low level of insulin would divert more energy to the insulin independent tissues and less to insulin dependent tissues." (PMID 17437648, 2007). "Insulin resistance in POKO mice was confirmed by an insulin tolerance test (ITT) in four-week-old male and female mice." (PMID 17465682, 2007). "The insulin resistance impairs insulin from suppressing lipolysis of triglycerides in SAT stores leading to increased release of free fatty acids." (PMID 17634130, 2007). "The role of insulin and insulin resistance would be an interesting subject in cancer prevention and treatment." (PMID 17953765, 2007). "We propose that, in a situation comparable to increased circulating insulin reflecting insulin resistance that increased plasma ASP is indicative of ASP resistance." (PMID 17490487, 2007). "These compounds have glucose-lowering,insulin-sensitizing, and antiobesity effects in animal modelsof insulin resistance and type 2 diabetes." (PMID 17497022, 2007). "After monitoring the women for nearly 5 y for CHD and strokes, the researchers looked for statistical associations between the occurrence of cardiovascular disease and markers of insulin resistance and reduced insulin secretion." (PMID 17760500, 2007). "Peripheral insulin resistance accompanied by high levels of insulin can therefore be said to be good for brain function." (PMID 17437648, 2007). "Initially, the beta cells of the pancreas can fully compensate for mild insulin resistance by increasing insulin production." (PMID 17589594, 2007). "Nevertheless, the relationship between leptin and insulin resistance in patients with chronic viral hepatitis (CVH) seems obscure at present; both presence and absence of association between serum leptin and insulin levels have been observed in CVH patients." (PMID 17540037, 2007). "Simple measures, such as fasting serum insulin, have been used as a surrogate of insulin resistance in previous epidemiological studies." (PMID 17650158, 2007). "Considering all these, this study was initiated to evaluate therole of CAR in mitigating oxidative stress and lipid accumulationin the insulin sensitive skeletal muscle in a well-characterizedmodel of insulin resistance." (PMID 17641743, 2007). "Surprisingly insulin resistance developed very early in life with elevated insulin levels and blood glucose compared to ob/ob mice." (PMID 17465682, 2007). "In the new interpretation insulin resistance was thought to take the role of quick insulin trigger and serve the same purpose." (PMID 17437648, 2007). "Although insulin resistance is regarded as the aetiological mechanism underpinning MS, direct quantification of insulin sensitivity can be difficult and complex in the general population." (PMID 17650158, 2007). "Insulin resistance in ob/ob mice was compensated for by increasing pancreatic insulin secretion, islet number, and size." (PMID 17465682, 2007). "As a result, people with insulin resistance have high blood levels of both insulin (hyperinsulinemia) and glucose (hyperglycemia)." (PMID 17760500, 2007). "Due to the increasing importance of identifying insulin resistance, a need exists to have a reliable mathematical model representing the glucose/insulin control system." (PMID 17850652, 2007). "Insulin resistance is defined as a condition when higher than normal insulin concentrations are needed to achieve normal metabolic responses." (PMID 17931417, 2007). "Insulin resistance occurs when increasing amounts of insulin are required to correctly regulate transport of plasma glucose into peripheral tissues." (PMID 17589594, 2007). "The impaired insulin-signaling pathway for PI 3-kinase activity plays a role in the development of insulin resistance." (PMID 16603055, 2006).
Insulin resistance (continued). "No other variant altered the AIRg, the ability of the β-cell to compensate for insulin resistance (disposition index, DI = SI *AIRg), or in 40 individuals, the maximal insulin secretory response to arginine (AIRmax)." (PMID 16869959, 2006). "Despite some controversy regarding the potential role of IL-6 in insulin resistance, IL-6 has been shown to inhibit insulin signaling and insulin action in isolated hepatocytes." (PMID 16787541, 2006). "Sympathetic stimulation effectively inhibits the antilipolytic effect of insulin by inducing insulin resistance." (PMID 17166287, 2006). "Along these lines, elevated glucosamine has also been found to cause a loss of sensitivity to stimulation of insulin and IGF-1 receptor tyrosine kinase activity in certain cells in culture, and leads to insulin resistance in experimental animals." (PMID 17109745, 2006). "Skeletal muscle is an important target for insulin action and insulin resistance here is a characteristic feature of type 2 diabetes." (PMID 16729893, 2006). "Overweight persons (BMI 25–29) also exhibit a spectrum of insulin sensitivities, which seems to suggest an inherited component to insulin resistance." (PMID 16948861, 2006). "Because the molecular mechanisms of insulin resistance are still being elucidated, it is indispensable to establish in vitro models of basal and insulin-mediated signal transduction to clarify these mechanisms and suggest treatments where appropriate." (PMID 16729893, 2006). "In our study, we evaluated the status of insulin resistance with fasting insulin, fasting glucose:insulin (G/I) ratio, and HOMAIR, all of which are parameters widely used to assess insulin resistance previously." (PMID 16603055, 2006). "Specifically, hyperthyroidism is characterized by decreased body weight, increased insulin and glucose indicative of insulin resistance as well as decreases in plasma lipids such as plasma cholesterol and triglycerides." (PMID 16472384, 2006). "Peripheral insulin resistance downregulate insulin uptake at the blood brain barrier and lead to CNS insulinopenia." (PMID 17096857, 2006). "Insulin resistance was evaluated with fasting insulin, fasting glucose/insulin ratio, and homeostasis model assessment index for insulin resistance (HOMAIR)." (PMID 16603055, 2006). "Published reports on these genes indicate their roles in insulin signalling and warrant further investigations on their functions in insulin resistance cases." (PMID 17217525, 2006). "Recent evidence has also suggested the role of adiponectin in the regulation of insulin action, energy homeostasis, obesity and insulin resistance." (PMID 16669997, 2006). "Although insulin resistance generally rises with increasing body fat content, one finds a broad range of insulin sensitivities at all levels." (PMID 16948861, 2006). "According to one theory of the pathogenesis of PCOS, a defect in insulin action leads to hyperinsulinemia and insulin resistance." (PMID 16146570, 2005). "The exposure of the liver to such large quantities of fructose leads to rapid stimulation of lipogenesis and TG accumulation, which in turn contributes to reduced insulin sensitivity and hepatic insulin resistance/glucose intolerance." (PMID 15723702, 2005). "A metabolic consequence of obesity, particularly the accumulation of intra-abdominal fat, is the development of insulin resistance, which leads to an increase in the secretion of insulin from the pancreas." (PMID 16288300, 2005). "In another study, significant decreases in insulin to glucose ratio were seen in the LoCHO group suggesting improved insulin sensitivity, especially in subjects with insulin resistance and higher baseline insulin levels." (PMID 16018812, 2005). "In general, insulin resistance expresses an imbalance between the amount of pancreatic insulin secreted in response to a glucose load and the levels of plasma glucose attained." (PMID 16269082, 2005).